RAX2 (retina and anterior neural fold homeobox 2)
Description:
May be involved in modulating the expression of photoreceptor specific genes. Binds to the Ret-1 and Bat-1 element within the rhodopsin promoter.
Synonyms: QRX; RAXL1; MGC15631; ARMD6; CORD11; RP95
Tractability: No criterion of Open Targets' tractability assessment is met for any kind of drug.
Gene: Protein-coding gene on chromosome 19 (3,769,089 to 3,772,228, reverse strand). Ensembl gene ENSG00000173976.
Subcellular location: Nucleus
Subcellular location (Human Protein Atlas): Nuclear speckles; Cytosol; Nucleoplasm
Gene Ontology:
Molecular function: DNA-binding transcription activator activity, RNA polymerase II-specific; RNA polymerase II cis-regulatory region sequence-specific DNA binding; DNA-binding transcription factor activity, RNA polymerase II-specific; DNA binding
Biological process: positive regulation of transcription by RNA polymerase II; regulation of transcription by RNA polymerase II; regulation of DNA-templated transcription
Cellular component: chromatin; nucleus
Genetic constraint (gnomAD): Loss-of-function variants: 4 observed, 5.82 expected, observed/expected ratio (o/e) 0.69, 90% interval 0.34 to 1.52. That is too few expected variants to judge how well the gene tolerates losing a copy. Missense variants: 275 observed, 224.79 expected, observed/expected ratio (o/e) 1.22, 90% interval 1.11 to 1.35. Synonymous variants: 133 observed, 108.35 expected, observed/expected ratio (o/e) 1.23, 90% interval 1.07 to 1.42.
Homologues: Orthologues: chimpanzee RAX2 (99% identical), macaque RAX2 (99% identical), dog RAX2 (92% identical), pig RAX2 (91% identical). Paralogues in human: RAX (61% identical), ARX (39% identical), PRRX2 (35% identical), VSX2 (35% identical), ALX4 (34% identical), ALX3 (33% identical), PAX7 (33% identical), OTX1 (32% identical), PAX3 (32% identical), PRRX1 (32% identical), SHOX2 (32% identical), OTX2 (32% identical), and 38 more.
Diseases named in the same sentence as RAX2 in open-access papers:
RAX2 is named in the same sentence as 14 diseases in open-access papers, as found by Europe PMC text mining. Sharing a sentence is not in itself a finding about the gene and the disease. The quoted sentences say what the papers report.
glioblastoma (4 papers, 2020 to 2024). The most malignant astrocytic tumor (WHO grade IV). "Knockdown of RAX2 increased DLG5 expression thereby inhibited the malignant biological behaviors of glioblastoma cells by activating the Hippo pathway." (PMID 32015336, 2020). "We demonstrated for the first time that the PABPC1/BDNF-AS/RAX2/DLG5 pathway plays the vital role in regulating the malignant biological behaviors of glioblastoma cells." (PMID 32015336, 2020). "RAX2 expression was elevated in glioma and knockdown RAX2 inhibited the malignant biological behaviors of glioblastoma cells." (PMID 32015336, 2020). "Overexpression of PABPC1, BDNF-AS, and DLG5 along with depletion of RAX2 inhibited malignant biological behaviors of glioblastoma cells." (PMID 32015336, 2020). "Our findings first revealed that PABPC1/BDNF-AS/RAX2/DLG5 module plays an important role in glioblastoma cells, provided insight into potential therapeutic targets to treat glioma." (PMID 32015336, 2020). "Knockdown of RAX2 produced tumor-suppressive function in glioblastoma cells and increased the expression of discs large homolog 5 (DLG5), leading to the activation of the Hippo pathway." (PMID 32015336, 2020). "Moreover, RAX2 knockdown inhibited the proliferation, migration and invasion, and promoted apoptosis in glioblastoma cells." (PMID 32015336, 2020). "In the present study, we first characterized RAX2 as an oncogenic factor in glioblastoma cells." (PMID 32015336, 2020). "This increase of RAX2 expression prompted that RAX2 may have possible biological effects on glioblastoma cells, therefore the biological behaviors of U87 and U251 cells were detected after stably constructing RAX2 silenced cells." (PMID 32015336, 2020). "The results indicated that DLG5 is involved in RAX2 regulation in glioblastoma cells." (PMID 32015336, 2020). "Retina and anterior neural fold homeobox 2 (RAX2), TUB like protein 1 (TULP1) and G protein subunit gamma transducin 2 (GNGT2) are associated with photoreceptor cells, with TULP1 being involved in retinitis pigmentosa and RAX2 playing a role in the malignant progression of glioblastoma." (PMID 39695086, 2024). "Additionally, RAX2 as a transcription factor may transcriptionally regulated the downstream gene in controlling behaviors of glioblastoma cells." (PMID 32015336, 2020). "With a variety of assays, we confirmed that BDNF-AS could bind to STAU1 and reduce the expression and stability of RAX2 mRNA via SMD, thereby further inhibited the malignant behaviors of glioblastoma cells." (PMID 32015336, 2020). "Moreover, BDNF-AS could elicit retina and anterior neural fold homeobox 2 (RAX2) mRNA decay through STAU1-mediated decay (SMD), and thereby regulated the malignant behaviors glioblastoma cells." (PMID 32015336, 2020).
autosomal recessive retinitis pigmentosa (2 papers, 2019 to 2021). Autosomal recessive retinitis pigmentosa (RP) is an autosomally recessive inherited retinal dystrophy leading to progressive loss of the photoreceptors and retinal pigment epithelium and resulting in blindness usually after several decades. "One of the called HDs was instrumental in defining a new association of biallelic variants in the RAX2 gene with autosomal recessive Retinitis pigmentosa." (PMID 34946927, 2021). "Here, we report the identification of RAX2 as a novel disease gene mutated in autosomal recessive retinitis pigmentosa (ARRP), a rod–cone type of IRD, in five unrelated families of Belgian, British, Italian, and Spanish origin." (PMID 30377383, 2019). "Biallelic RAX2 sequence and structural variants were found in five unrelated European index cases, displaying nonsyndromic autosomal recessive retinitis pigmentosa (ARRP) with an age of onset ranging from childhood to the mid-40s (average mid-30s)." (PMID 30377383, 2019). "The five identified HDs were validated by PCR and/or Sanger sequencing in the following patients: first, an HD of the first two exons of the RAX2 gene was identified in two reportedly unrelated subjects (a female and a male), who had a clinical diagnosis of autosomal recessive retinitis pigmentosa." (PMID 34946927, 2021).
retinal disease (2 papers, 2019 to 2025). "To conclude, we found biallelic pathogenic variants in RAX2 to be associated with ARRP, revealing RAX2 as a novel gene for recessively inherited rod-dominated retinal diseases." (PMID 30377383, 2019).
glioma (1 paper, 2020). A benign or malignant brain and spinal cord tumor that arises from glial cells (astrocytes, oligodendrocytes, ependymal cells). "In summary, we first found that PABPC1, BDNF-AS, and DLG5 were downregulated in human glioma tumors and cells, while RAX2 was upregulated conversely." (PMID 32015336, 2020). "In our study, we provided the endogenous expression and functions of PABPC1, BDNF-AS, RAX2, and DLG5 in human glioma tumor specimens and cells." (PMID 32015336, 2020).
microphthalmia (1 paper, 2020). Congenital or developmental anomaly in which the eyeballs are abnormally small. "RAX mutations result in microphthalmia, whereas RAX2 mutations are associated with cone–rod dystrophy or age‐related macular degeneration." (PMID 32144893, 2020).
ocular sarcoidosis (1 paper, 2022). A leading cause of inflammatory eye disease is sarcoidosis. "The rs149564368 (g.74267460C > T) of VSX2 was associated with higher susceptibility to ocular sarcoidosis, and the RAX2 rs76076446 is associated with susceptibility to macular thickness." (PMID 35656327, 2022).
retinal degeneration (1 paper, 2024). Degeneration of the retina. "Given that both p.(Arg79Gln) and p.(Ala61Thr) occur within this same domain, it is plausible that these variants impair RAX2 function in a similar manner, leading to the patient’s retinal degeneration." (PMID 39858579, 2024).
Retinal dystrophy (1 paper, 2019). Retinal dystrophy is an abnormality of the retina associated with a hereditary process. "Genetic etiologies of retinal dystrophy causing both autosomal dominant and recessive disease have been described in the literature and include RHO, RP1, BEST1, GUCY2D, RAX2, and RPE65." (PMID 31856884, 2019).
retinal disorder (2 papers, 2022 to 2025). Any disease or disorder of the retina. "This study highlights the importance of further exploring the regulatory functions and interactions of RAX2 to improve our comprehension of retinal development and discover new therapeutic interventions for retinal disorders linked to these cells." (PMID 40538981, 2025). "Our results suggested that RAX2 is significant in retinal development, underpinning its potential as a therapeutic target in related retinal disorders." (PMID 40538981, 2025). "Understanding RAX2’s interactions with key developmental genes like PAX6 and SOX2 is crucial for advancing gene therapy approaches for retinal disorders." (PMID 40538981, 2025). "The current signed-off version of Genomics England’s PanelApp Retinal Disorders virtual panel gene list (version v2.195) includes all six main CACD genes, plus CRX, NR2E3, NRL, RAX2 and also VSX2, but as low-evidence gene (red list)." (PMID 35656327, 2022).
RAX2 also shares sentences with these, for which no sentence is quoted: tumor (3 papers); cancer (1); cone-rod dystrophy type 11 (1); retinitis pigmentosa (1); thyroid cancer (1).